TNF (tumor necrosis factor)
Diseases named in the same sentence as TNF in open-access papers (continued):
Sharing a sentence is not in itself a finding about the gene and the disease.
infection (continued). "Endothelial and MΦ responses to infection have been characterized and include detection of proinflammatory cytokines (IL-1β, TNF-α, IL-8) and activation of transcriptional factor NF-κB." (PMID 34320039, 2021). "To dissect the protective roles of TIPE proteins, we analyzed CD45+, CD4+, CD8+, IFNg- and TNFα-secreting cells in the lung at day 13 after infection." (PMID 34939151, 2021). "Initiating anti-TNFα before the infection results in lethal infection with a mean time to death of 34 days." (PMID 35174101, 2021). "In essence, DAP12-/- and FcRγ-/- Hoxb8 neutrophils produced similar amounts of MIP-1α, RANTES and TNF upon infection with A. phagocytophilum." (PMID 33747981, 2021). "Alterations at the splenic cytokines, including decreased IFN-γ levels and increased TNF-α and IL-10, were observed after 19 days of infection." (PMID 34575795, 2021). "With regard to cytokine contents in the cell culture medium, the TNFα content of the ΔhtpG infection group was significantly lower than that of the WT and CΔhtpG infection groups (p < 0.01 and p < 0.05, respectively)." (PMID 34869065, 2021). "After continuous infection for 12 h, cell-derived exosomes induced M1 polarization of macrophage by enhancing CD11b protein, TNF-α, and iNOS mRNA levels, along with the decrease of Arg-1 mRNA level." (PMID 34136558, 2021). "Although the present meta-analyses raise concerns about the use of anti-TNFα agents to treat inflammatory conditions based on higher incidences of serious infections and cancer, it is important to interpret these results with caution." (PMID 34790122, 2021). "This bacteria stimulated immune cell responses (macrophages and dendritic cells derived from human monocytes) infected with these pathogens to reduce the infection by producing co-stimulatory and effector molecules (TNF-α, IL-6, IL-8, and iNOS)." (PMID 33919849, 2021). "Similar dependence on TNFα to maintain control of a pathogen has also been observed in other infections, including Mycobacteria." (PMID 35174101, 2021). "MAIT cells were found to be polarized to a Th1-like phenotype, with highest proportions, and numbers, of cells producing TNF, IFNγ, and GM-CSF, but few detectable IL-17-producing cells during the acute phase of infection (6 dpi)." (PMID 34272362, 2021). "HIV can cross the epithelial barrier when the junctions between the epithelial cells are loosened due to pro-inflammatory factors such as tumor necrosis factor (TNF) and/or by sustained activity of effector T-cells in the early stages of the infection." (PMID 33803543, 2021). "These preliminary results highlight the privileged status of TNFα on brain integrity in the context of infection." (PMID 34067023, 2021). "We observed that the proinflammatory cytokines TNFα and IL-12 were significantly decreased (p < 0.01) in the duodenum of infected animals (CPi and LPi) due to infection with L. infantum." (PMID 34207946, 2021). "S.pn infection led to significantly increased inflammatory cytokine levels of TNF-α, IL-1β, and IL-6 in BALF (p < 0.01)." (PMID 35111047, 2021). "The NF-κB-activation-pathway is regulated by LPS, generated during infection and the production of TNF-α and the activation of this pathway are central molecular events leading to the development of septic shock." (PMID 34502521, 2021). "The role of TNF-α in the normal immune response to infection iswell described and infectious complications resulting from inhibitorsof TNF are therefore to be expected." (PMID 34430870, 2021). "After 24 h of infection, the relative expressions of TNFα, IL-8, and IL-18 mRNA in the ΔhtpG infection group were significantly lower than those in the WT infection and CΔhtpG infection groups (p < 0.05)." (PMID 34869065, 2021). "For these experiments, we treated groups of mice with control or anti-TNFα antibody starting 2 days before infection as above." (PMID 35174101, 2021).
infection (continued). "We found that infection of both subsets with RV resulted in a low TNF-α and a high interferon (IFN, type I and type III) release whereby M-MΦ produced far more IFNs than GM-MΦ." (PMID 34975859, 2021). "Transcription levels of four major proinflammatory cytokines, IL6, IL8, IL1β and TNFα, were examined at different times post infection." (PMID 33712643, 2021). "Using RT-qPCR, we corroborated necroptotic events in line with microscopic observations despite an erratic expression of Tumor Necrosis Factor α (TNFα) throughout the four days of infection." (PMID 34608167, 2021). "Interferon-gamma (IFNγ) and tumor necrosis alpha (TNFα) are secreted by pro-inflammatory macrophages and are known stimulants of apoptotic pathways as a physiological mechanism in response to infection or injury." (PMID 34070547, 2021). "Prior studies have found that expression of key inflammatory cytokines known to be increased during infection with SARS-CoV-1 (IL-1β) and SARS-CoV-2 (TNFα and IL-6) is increased during infection with MHV-A59 as well." (PMID 34479991, 2021). "With the in-depth understanding of TNF-α inhibitors, certain possible safety risks are gradually discovered, including serious infection, malignancy and immunogenicity." (PMID 34627365, 2021). "Studies are ongoing to examine possible mitigation of proinflammation and acute tissue injury during infection in Mincle-/- mice (plus anti-TNFα treatment)." (PMID 34320039, 2021). "BMDMs treated with itaconate displayed increased secretion of TNF-α and a significant reduction in IL-10 secretion compared to untreated BMDMs in response to infection." (PMID 34350128, 2021). "Neutrophils are also recruited to the primary site of infection by the tissue-resident macrophages through the secretion of IL-8, TNF-α, and IFN-β." (PMID 34696397, 2021). "TNF-α is one of the inflammatory mediators playing a role in the systemic response to trauma and infection." (PMID 33664944, 2021). "Loss of SETDB2 with coronavirus infection led to increased production of inflammatory cytokines (IL-1β, TNFα, and IL-6) in Mφs via alterations in H3K9me3 at NFkB binding sites on inflammatory gene promoters following infection." (PMID 34479991, 2021). "TNF is a primary proinflammatory cytokine that plays crucial roles in modulating the immune response during the acute-stage of infection by Eimeria species." (PMID 34025594, 2021). "Regarding the differences among serotypes, statistically significant higher levels of TNF-α were expressed only after 2 h of infection by serotype c compared to serotypes a (p = 0.0354) and b (p = 0.0440)." (PMID 33802988, 2021). "Lm killing and vaccinated host protection during recall infection require TNFα, which CCR2+Ly6C+ monocytes are a major source." (PMID 34516896, 2021). "Results showed that the effects of H9N2 AIV infection and DATS treatment on the expression of TNF-α and IL-6 were most profound at 6 days post infection." (PMID 34412671, 2021). "Real-time quantitative PCR was used to detect the mRNA relative expression of pro-inflammatory cytokines, including TNF-α, IL-1β, IL-4, and IL-6 in the supernatant of endothelial cells 48 h after infection with influenza virus." (PMID 34414033, 2021). "TNF-α is a crucial proinflammatory cytokine required during the early phase of infection and also during a specific immune response." (PMID 34446765, 2021). "Infection with SPtA 9150 WT and ΔfepE, as well as ΔinvA as a control, induced similar secretion levels of TNF, which is induced and secreted via inflammasome‐independent signalling, ruling out a role for the LPS O‐antigen chains in macrophage priming." (PMID 33355403, 2021). "Critical insights into the M. abscessus pathogenesis emerged from a zebrafish infection model, which identified the importance of cording as a mechanism of immune evasion and the role of TNF signalling in controlling infection and granuloma formation." (PMID 34530447, 2021).
infection (continued). "Delving into antigen-presenting cell functionality, a lower activation state was evidenced by a reduced expression of the co-stimulatory molecule CD80 and decreased IL-1 and TNF-α production after in vitro infection with the parasite." (PMID 35046919, 2021). "The avian H7N9 (H7/SH2/13) also can infect human neurons and astrocytes cell lines, and thus the infection results in the increase of IL-6, IL-8, TNF-α, IFN-β, and CCL2." (PMID 33917837, 2021). "A protective immune response to infection is of the Th1 type, activated by the S epitopes and characterized by the synthesis of IFNγ, IL-2, and TNF-α, while a predominantly Th2 response, with IL-4, -5, -13 synthesis can have detrimental effects." (PMID 34946179, 2021). "In case of immune response, the tumor necrosis factor (TNF) and interleukin-17 (IL-17) signatures were noted after 24 h with multiplicities of infection of 0.1." (PMID 34571968, 2021). "In particular, S. aureus-induced infection determines a deregulated production of pro-inflammatory cytokines, including tumor necrosis factor alpha (TNF-α) and interleukin-6 (IL-6), as well as of several chemokines." (PMID 33430251, 2021). "Surprisingly, necrostatin-1 failed to reverse the cell viability decline in the PRV GD-WH infection group, but successfully restored the cell viability in the group treated with TNF-α/Smac mimetic/Z-VAD-FMK, a classical necroptosis activator." (PMID 34149651, 2021). "IL-8 was produced at basal level and its expression was enhanced upon infection, while the two others (IL-6, and TNFα) were mostly induced by L. monocytogenes." (PMID 34367171, 2021). "During infection and trauma, the secretion of pro-inflammatory cytokines including IL-1, IL-6, and TNF-α, induce the production of C-reactive protein (CRP), procalcitonin (PCT), ferritin, and serum amyloid A (SAA) as common inflammatory mediators." (PMID 35126355, 2021). "Exorbitant amounts of TNF-alpha and IL-6 were seen in the peritoneal lavage of mice after KPn infection which peaked at 12 h p.i. in untreated mice." (PMID 34135384, 2021). "In order to detect the anti-apoptosis effect of Ct infection, HeLa cells were infected with Ct for different time points and pretreated with 20 ng/ml TNF-α for 6 h, respectively." (PMID 34568091, 2021). "Leishmania antigen-stimulated peripheral blood lymphocytes also produce interferon gamma (IFN-γ) and tumor necrosis factor (TNF) in subclinical infection, but at lower levels than CL." (PMID 32830257, 2021). "Our results are also in line with a previous report demonstrating that following infection with HCoV-229E human macrophages strongly secrete TNF, but also produce IL-6 and some IFN-β." (PMID 33912475, 2021). "The manifestation of severe dengue infections occurs during the critical phase of the infection, and levels of pro-inflammatory cytokines, such as TNF-α and IL-6, become elevated, which leads to further disease progression and causes DHF/DSS." (PMID 34912307, 2021). "Survival and a less complicated course of infection correlated with early rise of low levels of pro-inflammatory cytokines including TNF-α." (PMID 34819932, 2021). "Tumor necrosis factor-alpha (TNF-α) is an acidic protein that is mainly produced by macrophages in response to infection and inflammatory irritation." (PMID 34795583, 2021). "IFN‐g, TNF‐a, IL‐6, and IL‐10 were all increased after challenge, but IL‐6 and IL‐10 levels dropped quickly 3 days post‐infection." (PMID 34176237, 2021). "The data showed that infection with H7N7 promoted cognitive impairment at 30 days p.i. and caused an increase of IFN-γ and TNF-α in both sera and brains at eight days p.i.." (PMID 33917837, 2021). "Overall, an observable trend of higher serum levels of IL-4 and TNF-α after two cycles of infection-treatment was apparent and diminished during the third cycle." (PMID 34956183, 2021).
infection (continued). "Reports of patients with encephalopathies due to local infection with Influenza virus in the brain have shown an increased transcription for IL-6, IL-10, and TNF-α in immune cells from the peripheral blood." (PMID 34916908, 2021). "Interleukins (IL) and tumor necrosis factors (TNF), for example, are secreted in response to inflammatory stimuli, such as infection by toxic substances/viruses/bacteria or injuries." (PMID 34445619, 2021). "The pro-inflammatory molecules commonly increased during the infection with influenza virus are the IL-6, TNF-α, and IL-1β." (PMID 33917837, 2021). "At 24 h post-infection, serum levels of IL-6, IL-17A, TNF-α, and IFN-γ were greatly reduced in IL-38-treated group, CCL2 and CXCL10 decreased at day 4, IL-1β and CCL-5 decreased on day 7 in the IL-38-treated group compared with group without IL-38 treatment." (PMID 33414457, 2021). "Being located on epithelial and mucosal surfaces, these cells initiate an immune response against A. baumannii by producing IL-8 and TNF-α to recruit and activate neutrophils at the site of infection." (PMID 33804894, 2021). "Proinflammatory cytokines, such as IL-6, IL-1β, and TNF-α, play an essential role in infection-induced inflammatory responses." (PMID 34829902, 2021). "There was altered TNF-α release following TLR7/8 stimulation in untreated infection (p=0.024 at 1-month, p=0.055 at 12-months), but this function was restored following late ART initiation." (PMID 34630420, 2021). "The levels of TNF-α were similar between the co-culture group and the co-aggregation group at 24 h post infection." (PMID 35071038, 2021). "Generally, TNF-α is key for granuloma formation and recruitment of immune cells to the site of infection." (PMID 33777000, 2021). "MoDCs presented a reduced production of IL-12 and TNF-α after 24 h of infection with the Tehuantepec strain, while BM-DCs showed diminished IL-12 secretion but higher IL-10 production 24 h post-infection." (PMID 33897690, 2021). "In contrast, TNF blockade by CrmD during wild type infection resulted in a reduction in pathology, leukocyte recruitment, and inflammatory cytokine production in the lungs." (PMID 34451529, 2021). "CD4+TNF-α+T cells were significantly higher in the low dose group than the high dose group at week 1 post-infection." (PMID 34484203, 2021). "The fluctuation in WBC count and TNF-α, IL-6 and IL-1β content in rat blood during the first week after infection were also monitored." (PMID 34521472, 2021). "TNF-α and IL-1β are acute-response cytokines appearing early after infection, followed by a more sustained increase in IL-6." (PMID 33995033, 2021). "Expression levels of tumor necrosis factor (TNF)-α after infection with SHIV-Ag85B were significantly higher than those after infection with SHIV-NI." (PMID 34686680, 2021). "The data in this critical study demonstrated that through Notch-1/IL-6 signaling, anti-TNF-α agents decreased ACE2 expression and shedding through TMPRSS2/TACE modulation and increased the susceptibility to infection." (PMID 34025650, 2021). "Analysis of lung cytokine levels revealed that the application of AMs prior to infection with IBV generally increased the expression levels of TNF in uninfected and infected offspring." (PMID 34400653, 2021). "They both regulated the intensity of immune responses to XPa in mice, and no severe inflammatory responses were observed in immunized mice (the levels of the inflammatory factors IL-6, TNF-α and IL-8 were lower than those of Infection group mice)." (PMID 34593766, 2021). "Tumor necrosis factor-α (TNF-α) is a cytokine mediating the immune response to infections, especially against intracellular pathogens." (PMID 34069740, 2021). "Whereas AM mainly produce (TNF)-α after 6h of infection with conidia, murine AEC mainly produce (IL)-6 after 10h." (PMID 34898608, 2021).
infection (continued). "VLP immunizations with or without adjuvant CpG showed significantly lower levels of inflammatory cytokine TNF-α in the brain upon challenge infection compared to the unimmunized naïve control (Naïve+cha)." (PMID 33922808, 2021). "Macrophages play an important role in the secretion of inflammatory cytokines such as TNF-α and IL-6, host defense against infection, and recovery of damaged tissues." (PMID 33407886, 2021). "Mice with stable Cp1038 infection treated with anti-TNFα antibody began to die 2 weeks after the treatment was initiated, and the lungs and spleens showed grossly severe disease not present in the isotype-treated controls." (PMID 35174101, 2021). "As a second pathogenic mechanism, the activation of polyclonal B lymphocytes stimulating autoantibody production is proposed, following increased infection rates due to immunosuppression by anti-TNFα agents." (PMID 34616488, 2021). "Herein, the expression of CASP8, CASP7, and CASP 3 was significantly up-regulated after infection, with the expression of TNFα significantly up-regulated at 6 and 24 h post-infection." (PMID 34451461, 2021). "The levels of TNF-α at 24 and 48 h were higher than that of Dlm before administration (P<0.05), but were similar to that of the infection group (P>0.05)." (PMID 35003120, 2021). "The sustained transcriptional upregulation of immune genes in the MOK023 group was supported by pathway analysis – the overrepresentation of both the NF-κB and TNF signalling pathways was sustained for longer after infection with MOK023." (PMID 34740333, 2021). "Together, these findings confirmed that the LmGAPDH contained in EVs inhibits TNF-α expression in macrophages during infection via posttranscriptional repression." (PMID 34534548, 2021). "Increased TNF-α and IL-10 production followed in vitro infection of BMDMs with whole parasites (blue bars)." (PMID 33912181, 2021). "During infection, neutrophils produce substantial amounts of TNF-α, and consequently, neutrophil depletion in Lm-infected mice leads to decreased TNF-α levels and increased bacterial load." (PMID 34659211, 2021). "These marginal positive correlations were also seen at 30 days post-infection, however, only the positive correlation between IFN-γ and TNF-α carried over to the 90-day post-infection time point." (PMID 34026898, 2021). "While TNF release was similar in LPS-stimulated in MDMs from males and females, the infection by C. burnetii lead to a significant decreased of cytokine level in MDMs from males compared to females (mean 103 vs. 211 pg/mL, respectively, p=0.004)." (PMID 34987498, 2021). "In the present study, we compared the expression levels of the Th1-type cytokines IL-1β, TNF-α and IL-6 and the Th2-type cytokines IL-4 and IL-10 in susceptible host BALB/c mice and resistant host M. fortis on different days post-infection with S. japonicum." (PMID 34689797, 2021). "The expression levels of TNF-α, IL-6, IL-8, and IL-10 at different infection time points were higher than those in the control group, especially at 36 hpi." (PMID 33597007, 2021). "Activated macrophages can produce enough ROS to kill pathogens and resolve infection, while its excessive production of TNF-α leads to liver inflammation, injury, and liver functional failure." (PMID 34434948, 2021). "The PLS showed that the levels of GMCSF, Fractalkine, IFNg, ITAC, IL-1ß, IL-2, IL-5, IL-7, IL-8, IL-10, IL-12, IL-17α, IL-21, IL-23, MIP-1ß, and TNFα had higher impact on the separation between the uninfected and the pre-infection cohort." (PMID 33731158, 2021). "TNF-α is elevated in infections of PRRSV, LCMV, Salmonella Typhimurium and bacteria targeting the respiratory system, e.g., Mycobacterium tuberculosis." (PMID 34113341, 2021). "A different pattern of cytokine production was observed in intestinal samples, with C. rodentium single infection leading to a modest increase in pro-inflammatory cytokines (TNF, IL-6, IFN-γ, and IL-17) and IL-10 in the colon and cecum." (PMID 33440153, 2021).